GREM1 (gremlin 1, DAN family BMP antagonist)
Diseases named in the same sentence as GREM1 in open-access papers (continued):
Sharing a sentence is not in itself a finding about the gene and the disease.
tumor (continued). "GREM1 expression in macrophages (F4/80+) of liver infiltrating tumor tissues was enhanced in Exo-scramble-treated mice compared with PBS-treated mice, and GREM1 expression in macrophages of liver metastases was significantly reduced in mice pre-treated with Exo-KD 1# and Exo-KD 2#." (PMID 40849639, 2025). "Additionally, in colorectal cancer, GREM1 has been implicated in EMT and extracellular matrix (ECM) remodeling, enhancing tumor invasiveness." (PMID 40066442, 2025). "By promoting the activation of specific signaling pathways, GREM1 may enhance tumor cell invasion and metastasis." (PMID 40066442, 2025). "In previous studies, GREM1 plays different roles in the development of different tumor cells." (PMID 38970064, 2024). "Our results suggested that GREM1 exhibits higher levels of expression in BCa in comparison with normal tissues, indicating that it might have a significant role in tumor progression." (PMID 37605239, 2023). "Yet, recent research has revealed that GREM1 is involved in the control of tumor growth." (PMID 37605239, 2023). "Furthermore, A549 cells incubated, or overexpressing GREM-1, showed an increase in the tumor volume, migration, proliferation, and invasion potential." (PMID 35203511, 2022). "Characteristically, GREM1 induces massive infiltrations of immunosuppressive cells incorporating macrophages, Tregs, and MDSCs, repressing immune cells to identify and eliminate tumor cells." (PMID 36091126, 2022). "T-cell exhaustion was detected in the tumor microenvironment of PDAC with GREM1 expression." (PMID 36091126, 2022). "Compared with normal tissues, GREM1 was significantly upregulated in tumor tissues." (PMID 35883579, 2022). "Interestingly, the increasing level of serum GREM1 occurred in bigger tumor diameters and advanced histopathological grades, as the primary result of GREM1 representing a formidable stromal factor and functioning as stroma modulation." (PMID 36091126, 2022). "It suggested that GREM1 promoting stromal construction may contribute to the blockade of matrix degeneration and indicated its crucial role in tumor growth from another aspect." (PMID 36091126, 2022). "PDAC secured the augmentation of GREM1 expression to perform its all-around tumor promotion." (PMID 36091126, 2022). "GREM1 overexpression significantly increased tumor metastasis to the lung." (PMID 35883579, 2022). "FOXL1 and TGF-β may explain, at least in part, the polarization of CAFs into tumor-promoting GREM1+ CAFs and tumor-retarding ISLR+ CAFs." (PMID 33197448, 2021). "Finally, up‐regulated miR‐218 or down‐regulated GREM1 reduced tumour growth and liver metastasis in vivo." (PMID 33107676, 2020). "Our results showed that GREM1 depletion inhibited tumor growth and lung metastasis in vivo." (PMID 33287358, 2020). "Furthermore, Grem1 has been found to be one of the most upregulated genes in the tumor microenvironment." (PMID 32756430, 2020). "The growth of tumors at the primary site showed that Grem1 knockdown cells grew much slower than control cells, leading to a dramatic reduction in tumor volume (mean ± SD (mm3): 1037.812 ± 677.76 (MTV/TM-011-shCtrl-luc) vs. 41.39 ± 69.33 (MTV/TM-011-shGrem1-luc), six mice/each group)." (PMID 33287358, 2020). "Finally, effects of miR‐218 and GREM1 on tumour formation and liver metastasis were evaluated in xenograft tumour‐bearing nude mice." (PMID 33107676, 2020). "Notably, there was a significant reduction in the mean tumor burden of the long bones of anti-Grem1 antibody-treated mice compared to control-treated mice in two of the three treatment regimens (pretreatment p = 0.0008, day 3 treatment p = 0.0022)." (PMID 32756430, 2020). "Likewise, a significant increase in BM stromal Grem1 expression was observed in tumor-bearing bones of two commonly used preclinical mouse models of MM." (PMID 32756430, 2020).
tumor (continued). "Given that Grem1 expression is increased in the MM BM microenvironment in vivo and acts to promote MM PC proliferation in vitro, we hypothesized that functional blockade of Grem1 may reduce MM tumor growth." (PMID 32756430, 2020). "As such, GREM1 may represent a microenvironmental factor that is frequently upregulated in MM patients despite their diverse tumor genetics and, therefore, may represent a suitable therapeutic target for the majority of MM patients." (PMID 32756430, 2020). "Grem1 may have different roles in different tumor types, but this may be dependent on the experimental setup, the analysis of expression in complete tumors vs stromal expression specifically, and/or the determining the levels of RNA vs protein." (PMID 31533776, 2019). "Within the tumor-stroma niche, inflammatory cells secreting cytokines may also contribute to GREM1 expression by CAFs." (PMID 31533776, 2019). "Expression of VEGFR2 in HUVEC and HBMEC in vitro and in the DIPG tumor vasculature in vivo also supports the possibility that GREM-1 acting through VEGFR2 may modulate DIPG angiogenesis." (PMID 29435175, 2018). "Furthermore, over-expression of GREM1 initiated tumorigenesis and promoted tumor cell proliferation." (PMID 28977865, 2017). "This inflammatory response may recruit the fibroblasts into the tumor, and induce GREM1 expression in these fibroblasts." (PMID 28346486, 2017). "To assess whether Grem1 is reduced as a consequence of stromal Hh activation in the tumours, we used RNA ISH and semi-quantitatively evaluated the staining intensity." (PMID 27492255, 2016). "In addition, whether the regulation of CAF-exo in PMN formation and distant metastasis through the GREM1/SHH/FGF4 axis can similarly influence orthotopic tumor properties to promote the distant metastasis needs to be further investigated." (PMID 40849639, 2025). "This suggests that GREM1 may influence tumor cell migration and invasion through EMT modulation." (PMID 40066442, 2025). "GREM1 may also impact immunotherapy efficacy by influencing tumor genetic stability." (PMID 40066442, 2025). "One idea is that GREM1 may function differently in tumor cells compared to CAFs." (PMID 37615860, 2023). "Importantly, the KaLwRij mice with the greatest 5TGM1 tumor burden, as determined by bioluminescent imaging, displayed the greatest expression of Grem1, with a significant positive correlation between Grem1 expression and tumor burden observed (p = 0.0018, r = 0.666)." (PMID 32756430, 2020). "Importantly, we found a positive correlation between tumor burden and Grem1 expression." (PMID 32756430, 2020). "Given that anti-Grem1 antibody treatment demonstrated the greatest antitumor effect during early stages of disease, where tumor burden was still limited, this therapy would be well suited in the maintenance phase of treatment where MM PC tumors may still be widespread, but of small size." (PMID 32756430, 2020). "Moreover, GREM1 expression correlated with mesenchymal marker expression in tumor samples." (PMID 31533776, 2019). "GREM1 encodes a protein whose expression is weak or absent in normal colorectal epithelium but increases in CRCs, especially those with serrated histology and low tumor stage." (PMID 30563495, 2018). "Therefore, although the tumor alone may not have invasive properties, if it could cause inflammation resulting in tissue damage and stromal reaction, this may result in recruiting the GREM1-expressing myofibroblasts in the tumor stroma." (PMID 28346486, 2017). "GREM1 accelerates the EMT process by synergistically interacting with these genes, thereby enhancing the invasion and metastatic capabilities of tumor cells." (PMID 40066442, 2025). "PPI analysis revealed COL10A1, POSTN, SPP1, MMP11, and GREM1 as key hub genes in extracellular matrix (ECM) remodeling and tumor progression." (PMID 40826767, 2025).
tumor (continued). "Ginisortamab, by blocking the interaction between GREM1 and BMP, restores BMP signaling, potentially suppressing tumor stem cell proliferation and self-renewal while reducing the risk of chemoresistance and relapse." (PMID 40066442, 2025). "GREM1 facilitates ECM degradation and remodeling, disrupting normal tissue architecture to create conditions favorable for tumor cell migration and invasion, and also impacts immune cell function within the TME." (PMID 40066442, 2025). "MMP2, COL6A3, PRRX1, COL1A2, GREM1 and SNAI2 are integral to the EMT process, a key driver of metastasis that allows tumor cells to detach and invade distant tissues." (PMID 39920655, 2025). "This suggests that CAF-derived GREM1 and GAS6 primarily contribute to skewing macrophages toward an M2 phenotype within the tumor microenvironment (TME)." (PMID 40940956, 2025). "Previously, we described a prognostic model comprising five DNA methylation markers (i.e., GREM1, GATA5, LAD1, NEFH, and NEURL) in combination with clinicopathological characteristics (i.e., age at diagnosis, sex, Fuhrman grade, tumor size, and TNM stage)." (PMID 40820938, 2025). "Since research on GREM1 in LUAD is relatively limited, our study is the first to elucidate the role of GREM1 in regulating the tumor immune microenvironment." (PMID 40066442, 2025). "Knockdown of GREM1 in CAF-exo significantly improved survival and delayed death in tumor-bearing mice." (PMID 40849639, 2025). "Overexpression of GREM1, as observed in HMPS, acts as a BMP antagonist, thus allowing the cells to conserve stem properties and develop into neoplasia." (PMID 37249599, 2023). "The qRT-PCR analysis of 20 pairs of BC and adjacent non-tumor tissues showed that the expression of PDGFRB, COMP, GREM1, and FRRS1 was higher in BC tissues than in non-tumor tissues." (PMID 36895470, 2023). "Experimental studies using animal and human models have shown that increased expression of GREM1 can induce epithelial dedifferentiation through BMP signaling and initiate gut cells neoplasia." (PMID 37249599, 2023). "GREM1 protein was investigated in PDAC by IHC staining, and the results found that GREM1 at the protein level was elevated in tumor tissues in contrast with normal pancreatic tissues." (PMID 36091126, 2022). "Among the downregulated genes were several known to activate proliferation of tumor cells (NOTCH1, HMGA2, PTK2, FOSL1, GREM1 and EGR1)." (PMID 35885035, 2022). "It was also shown that tumor cells alone can modulate the gene expression profile of naïve MSCs, including IL-6, BST2, ADAMTS12, MX2, LOXL2 and GREM1." (PMID 34513701, 2021). "When investigating the mRNA expression of COL1A2, POSTN, GREM1, MMP1, and MMP9 in patient material, we found all five genes to be upregulated in HNSCC tumor tissue compared to normal oral tissue." (PMID 34283070, 2021). "PVT1 silencing also modulated the miR-128-3p/Gremlin 1 (GREM1) axis resulting in inhibition of the bone morphogenetic protein (BMP) signaling pathway and tumor growth." (PMID 34322395, 2021). "The mean mRNA expression of TGFB3 (P = 0.0313), TIMP1 (P = 0.0469), GREM1 (P = 0.0156), and CTGF (P = 0.0313) were all increased in tumour stroma EVs compared to normal stroma EVs." (PMID 34596356, 2021). "This study suggests that upregulated miR-137 suppresses the tumor progression in CC via blocking the TGF-β/smad pathway by binding to and negatively regulating GREM1." (PMID 31143092, 2019). "Gremlin-1 has been associated with improved survival in locally advanced Stage II and III CRC, and could not be detected in the WT tumor proteome but was highly expressed in the G12V tumor (GREM1↑G12V) and showed an 11.1-fold higher mRNA level in the G12V tumor, in accordance with the proteome data." (PMID 31805664, 2019). "However, it remains unclear which cells are the source of GREM1 in the tumor biopsies." (PMID 31694641, 2019).
tumor (continued). "Reconstitution of N-MSCs with four genes, GREM1, LOXL2, ADAMTS12 and ITGA11 that contributed to the T-MSC phenotype increased their ability to promote primary tumor cell dissemination." (PMID 29503225, 2018). "GREM1 and the BMP ligand BMP5 were enriched significantly in the stromal fraction, in keeping with the results from the mouse model, whereas tumour cells expressed BMP4 in several cases." (PMID 27492255, 2016). "Thus, GREM1 may increase tumor proliferation through stromal effects." (PMID 24586997, 2014). "Although there was no single tumor marker, we identified a set of genes (Bone Morphogenetic Protein inhibitors GPC3, GREM1, FSTL3, and FST) in which at least one gene was over-expressed in 100% of the tumor samples." (PMID 23667740, 2012). "At least one of the inhibitors GPC3, GREM1, FSTL3, and/or FST were over-expressed (FC > 1.5) in 100% of tumor samples." (PMID 23667740, 2012). "Moreover, GREM1 modulates the TGF-β signaling pathway, further increasing the metastatic potential of tumor cells." (PMID 40066442, 2025). "Previously, we developed a prognostic biomarker model containing five DNA methylation markers (GREM1, GATA5, LAD1, NEFH, and NEURL) in combination with clinicopathological characteristics including age at diagnosis, sex, Fuhrman grade, tumor size, and TNM 3rd edition staging system." (PMID 40820938, 2025). "Neither TGF-B1, BMP4 and GREM1 transcript levels nor ID1 and pSMAD2 protein expression were significantly associated with survival in either tumour or stromal compartments." (PMID 40826447, 2025). "Immunofluorescence in liver-infiltrating tumor tissues showed that AAV-SHH or AAV-FGF4 successfully activated the positive feedback regulation between FGF4/SHH and GREM1 in macrophages (F4/80+), which contributed to an increase in CD206+F4/80+ macrophages and a decline in CD8+CD3+ T cells." (PMID 40849639, 2025). "Knockdown of GREM1 expression in CAF-exo significantly reduced M2-polarized macrophages (CD206+F4/80+) and enhanced the infiltration of CD8+CD3+ T cells in liver-infiltrating tumor tissues." (PMID 40849639, 2025). "The druggability of PDPN, PRSS3, GREM1, and LGALS1, alongside the established relevance of FAP, provides multiple entry points for stromal-directed interventions that could complement tumor cell–targeted therapies." (PMID 41198614, 2025). "Aberrant expression of GREM1 could promote tumor angiogenesis, extracellular matrix remodeling, and suppression of BMP-mediated anti-tumor signaling, thereby accelerating tumor cell proliferation and migration." (PMID 41048340, 2025). "Notably, in EGFR-mutant LUAD, GREM1 overexpression perpetuates PI3K/AKT/mTOR pathway activation, sustaining tumor cell survival and proliferation, which consequently attenuates the efficacy of EGFR-TKIs such as osimertinib." (PMID 41048340, 2025). "While these studies highlight the role of GREM1 in tumor proliferation, migration, and invasion, they do not fully address its impact on the immune microenvironment." (PMID 40066442, 2025). "Similarly, CTHRC1+GREM1+ myCAF communicated with SPP1+ macrophages and tumor cells through integrin signaling, where collagen/integrin pairs and FN1/integrin pairs were prevalent." (PMID 39075108, 2024). "Moreover, their responses to the tumor microenvironment differ, exemplified by STAT1 and GREM1 upregulation in HOSE1C and HOSE2C, respectively." (PMID 39634630, 2024). "However, they significantly differed in terms of marker genes (AKR1C1, FOSL1, LIF, and THAP2 vs. WNT5A, GREM1, TNC, and MMP1), tissue origins (normal vs. tumor), and organ preferences." (PMID 38744958, 2024). "In particular, CTHRC1+GREM1+ myCAF expressed high levels of collagens, including type-1 (COL1A1, COL1A6), type-3 (COL3A1), type-5 (COL5A2), and type-6 (COL6A1), which contribute to tumor cell migration and proliferation through collagen/integrin interactions." (PMID 39075108, 2024).
tumor (continued). "We verified this by plotting the CTHRC1+GREM1+ myCAF, SPP1+APOE+ TAM, and EMT signatures from previous parts of our study, which showed clear overlays, supporting the co-localization of fibroblasts and macrophages while promoting the pro-tumor TME." (PMID 39075108, 2024). "To address this hypothesis, we first conducted expression plots of CTHRC1, GREM1, SPP1, and APOE in the TCGA cohort, which were all significantly enriched in tumor samples versus control." (PMID 39075108, 2024). "Given the lack of amino acid homology between GREM1 and FGF1/2 ligands, it will be interesting to explore whether GREM1-mediated FGFR1 signaling contributes to normal biological processes and/or other human tumor phenotypes." (PMID 37615860, 2023). "In particular, IL6 and BST2 were significantly induced in all naïve MSCs after 3 days’ coculture with primary tumor cells, whereas the expressions of ADAMTS12, MX2, LOXL2 and GREM1 varied and displayed transient induction during the course of the coculture assay." (PMID 34513701, 2021). "Methylation of GREM1, GATA5, LAD1, NEFH, NEURL, and SFRP1 was associated with poor ccRCC-specific survival, independent of age, sex, tumor size, TNM stage or tumor grade." (PMID 33947447, 2021). "Here, we identified gremlin 1 (GREM1) and immunoglobulin superfamily containing leucine-rich repeat (ISLR), specifically and distinctly expressed by different types of CRC CAFs, as important regulators of BMP signaling within the tumor microenvironment." (PMID 33197448, 2021). "Our results show a significantly higher mRNA expression of MMP1, MMP9, POSTN, GREM1, FMOD, and COL1A2 in tumor biopsies compared to normal tissue, but the significant difference between responder and non-responder groups was only found for the expression of FMOD mRNA." (PMID 34283070, 2021). "PVT1 can counteract the inhibitive expression of gremlin 1 (GREM1) through sponging miR-128, thereby affecting the downstream proteins BMP2 and BMP4-mediated signaling pathway, thus maintaining the proliferative activity of tumor cells." (PMID 31380270, 2019). "Elevated expression level of GREM1 in tumor biopsies correlate with adverse outcome irrespective of the expression level of the BMPs in the biopsy." (PMID 31694641, 2019). "Immunohistochemical staining of these proteins in biopsies from human OvCa peritoneal implants showed mesothelial‐derived (calretinin‐positive) spindle‐like cells in the stroma tissue surrounding tumour nodules, overlapping with areas with marked staining for MMP1, IL‐33, EGR1, TSP1, and GREM1." (PMID 28247413, 2017). "A study investigating the methylation status of GREM1 promoter CpG islands in four RCC cell lines—SKRC1, SKRC10, SKRC52, and SKRC59; 150 tumor samples from patients with sporadic ccRCC revealed heavy methylation in the cell lines and tumor samples." (PMID 26198328, 2015). "In addition, two members of the transforming growth factor beta superfamily, GREM1 and inhibin beta A (INHBA), showed markedly increased expression specifically in the tumor stroma." (PMID 19187537, 2009). "We speculate that GREM1 may regulate immune cell recruitment and localization in the TME by enhancing specific chemokine expression or activity, thus contributing to both antitumor immunity and tumor immune evasion." (PMID 40066442, 2025). "The expression of GREM1, PD-L1, CD206, and CD8 was detected in paraffin-embedded tumor tissues and adjacent tissues of NSCLC patients (n = 30), and the enhancement of the expression of GREM1, PD-L1, and CD206, as well as the attenuation of the expression of CD8 were observed in tumor tissues." (PMID 40849639, 2025). "Additionally, GREM1 contributes to T cell exhaustion by upregulating immune checkpoints like CTLA-4 and PD-1 and overactivating key signaling pathways, thereby impairing antitumor immunity and accelerating tumor progression." (PMID 40066442, 2025).